MCL1 (MCL1 apoptosis regulator, BCL2 family member)
Diseases named in the same sentence as MCL1 in open-access papers (continued):
Sharing a sentence is not in itself a finding about the gene and the disease.
pancreatic cancer (continued). "If this were the case, inhibition of both Bcl-xL and Mcl-1 could sensitize TRAIL-resistant pancreatic cancer cells more efficiently than Bcl-xL alone." (PMID 26506422, 2015). "Mcl-1 siRNA transfection significantly promoted MIA PaCa-2 pancreatic cancer cells apoptosis." (PMID 24025188, 2013). "Whether MCL-1 is also induced by the NF-κB pathway in pancreatic cancer cells, as it has been shown for BCL-XL, is unknown at the moment." (PMID 18652674, 2008). "Moreover, at least one study has demonstrated that inhibition of ERK signalling in pancreatic cancer cell lines leads to downregulation of Bcl-2 and other antiapoptotic proteins, including MCL-1." (PMID 15956974, 2005). "Thus, the FBXW7/MCL1 axis may be a promising therapeutic tool to overcome refractory pancreatic cancer." (PMID 29348852, 2017). "In addition, the anti-cancer effect of chidamide in pancreatic cancer may relate to regulation of Mcl-1 degradation." (PMID 27875574, 2016). "Furthermore, chidamide treatment or Mcl-1 knockdown significantly induced cell growth arrest in pancreatic cancer cell lines and primary cells, and Mcl-1 overexpression could reduce this cell growth inhibition." (PMID 27875574, 2016). "Chidamide decreased O2 consumption and ATP production to inhibit aerobic metabolism in both pancreatic cancer cell lines and primary cells, similar to knockdown of Mcl-1, while overexpression of Mcl-1 in pancreatic cancer cells could restore the aerobic metabolism inhibited by chidamide." (PMID 27875574, 2016). "Also a study on pancreatic cancer cells evaluated Mcl-1 as a target for radiosensitization." (PMID 26223311, 2015). "Furthermore, Mcl-1 in pancreatic cancer may act as a potent marker to analyze the therapeutic effects of AZD5582." (PMID 26314849, 2015). "Therefore, high MCL-1 might protect pancreatic cancer cells from hypoxia and oxidative stress during tumorigenesis." (PMID 18652674, 2008). "Taken together, our studies have shown the possibility of simultaneously targeting two key players of the apoptotic network in pancreatic cancer: c-FLIPL and Mcl-1 upon DL/gemcitabine treatment." (PMID 39753884, 2025). "Real-time PCR was employed to assess changes in the mRNA expression of the apoptosis-related markers, Bax and Mcl-1, in MIA-PACA2 pancreatic cancer cells following treatment with Mito-FF at varying concentrations." (PMID 39859498, 2025). "Upregulation of bcl-2, Bcl-xL, and Mcl-1 and downregulation of Bax and NOXA lead to gemcitabine resistance in pancreatic cancer." (PMID 38884675, 2024). "Especially, compound 2g mediated cancer cell proliferation blockage and induced apoptosis in pancreatic cancer MIA PaCa-2 cells, and rapid down-regulation of Mcl-1 and c-Myc oncoprotein were observed after 2g treatment." (PMID 36656085, 2023). "It is reported that Sorafenib decreased constitutive STAT3 phosphorylation (Tyr705) as well as Mcl-1 and Bcl-xL expression in a dose-dependent manner to enhance TRAIL-mediated apoptosis in pancreatic cancer cell lines." (PMID 36975494, 2023). "Overall, Tan IIA has the potential to trigger apoptosis in pancreatic carcinoma by inhibiting the anti-apoptotic proteins of TCTP, Mcl-1, Bcl-xL and initiating the Caspase pathway’s activation." (PMID 37964867, 2023). "In a pancreatic carcinoma study, it was found that the increased concentration of Tan IIA led to an increase in levels of Bax and Caspase-3, while the decrease of TCTP, Mcl-1, and Bcl-xL, thus inducing BxPC-3 cells cell apoptosis." (PMID 37964867, 2023). "Mcl-1 and FLIP proteins were undetectable in normal pancreas tissues but detected in the pancreatic tumor tissues." (PMID 29409480, 2018). "This is highly possible, because survivin, Mcl-1, XIAP, and cIPA2 play critical roles in pancreatic cancer resistance to treatment, and it is also known that survivin, Mcl-1 and XIAP are involved in latent CSC drug resistance and function." (PMID 30285798, 2018).
pancreatic cancer (continued). "We also confirmed downregulation of MCL-1 upon KPT-6566 treatment in lung, prostate and pancreatic cancer cell lines." (PMID 28598431, 2017). "MCL1, which is a target of FBXW7 and a member of the BCL2 protein family, is an anti-apoptotic protein that has been reported to be overexpressed in pancreatic cancer cells and clinical tissue samples and is correlated with advanced disease." (PMID 29348852, 2017). "Our findings are in line with previous observations in pancreatic cancer, in which cell death by another BH3-mimetic was enhanced by blocking the binding of Usp9X to Mcl-1 in vitro and in vivo." (PMID 26872380, 2016). "We firstly investigated the effect of chidamide on Mcl-1 expression in BxPC-3 and PANC-1 pancreatic cancer cell lines." (PMID 27875574, 2016). "The pancreatic cancer cell lines BxPC-3 and PANC-1 were treated with chidamide, resulting in Mcl-1 degradation accompanied by induction of Mcl-1 ubiquitination." (PMID 27875574, 2016). "Activity of compounds 1–4 against Bcl‐2 family proteins including binding inhibition (IC50) of FITC‐mNoxa to Mcl‐1, binding affinity constant (Ki), and cell growth inhibition (IC50) of pancreatic cancer cells lines MiaPaCa‐2 and BxPC‐3." (PMID 26616140, 2016). "In terms of human pancreatic cancer, ABT-737 and obatoclax, which inhibits Bcl-2, Bcl-xL, and Mcl-1, were shown to enhance the TRAIL sensitivity of pancreatic cancer cell lines." (PMID 26506422, 2015). "Thus, the modulation of these proteins is unlikely to be associated with LBH589-mediated potentiation of TRAIL-induced apoptosis in these cell lines; rather, increase in Bcl-2 and Mcl-1 may counteract LBH589's effect in sensitizing pancreatic cancer cells to TRAIL-induced apoptosis." (PMID 20442774, 2010). "MCL1 amplification and overexpression have been reported in various human cancers, including hematological malignancies and solid tumors (e.g., NSCLC, breast, ovarian, prostate and pancreatic cancers)." (PMID 32645016, 2020). "In the present study, changes of expressions of anti-apoptotic proteins such as bcl-2, mcl-1, and transporter proteins were examined in pancreatic cancer cells co-cultured with TAMs, but no significant changes were observed (data not shown)." (PMID 30537992, 2018). "The basis for this potential, and the initiation of this study is that upregulation of antiapoptotic proteins, survivin, Mcl-1, XIAP, and cIPA2 are strongly involved in pancreatic cancer resistance, and that FL118 has been found to inhibit such gene expression in CRC and head-&-neck tumors." (PMID 30285798, 2018). "In addition, reduced FBXW7 expression enhanced tumor cell proliferation, migration, and invasion and the sensitivity of pancreatic cancer cells to gemcitabine and nab-paclitaxel was regulated by FBXW7 via MCL1 accumulation." (PMID 29348852, 2017). "However, the apoptosis induced by MCL-1 suppression was partially mediated through BAX in rheumatoid arthritis synovial fibroblasts and in pancreatic cancer cells." (PMID 28659182, 2017). "In human pancreatic cancer cells, inhibition of ERK1/2 activities caused downregulation of antiapoptotic proteins BCL-2, MCL-1, and BCL-Xl without affecting the proapoptotic proteins BAX and BAK." (PMID 27656657, 2016). "Alternatively, without TRAIL, the simultaneous knockdown of Bcl-xL and Mcl-1 induced apoptosis via Bax activation in pancreatic cancer cells." (PMID 26506422, 2015). "In contrast, only 12 of 17 cases of non-metastatic pancreatic cancer tissues show Mcl-1 expression (left)." (PMID 24025188, 2013). "The expression of Mcl-1 correlated with pancreatic cancer metastasis (p < 0.05) and TNM staging (p < 0.01), but not with tumor size or differentiation status." (PMID 24025188, 2013).
pancreatic cancer (continued). "To assess it and to further clarify the molecular mechanisms possibly involved, we pointed our attention on MCL-1: the anti-apoptotic member of the B-cell lymphoma 2 family (BCL-2), whose protein levels correlate with malignancy, and drug resistance in many tumors, including pancreatic cancers." (PMID 35884957, 2022). "The pancreatic cancer cell line AsPC‐1, which does not overexpress Mcl‐1, was also evaluated." (PMID 28670766, 2017). "SCH772984 potentiates the cytotoxic effect of CuB on pancreatic cancer cells through complementary inhibition of EGFR, PI3K/Akt/mTOR, STAT3 and ERK signaling, followed by an increase in the pro-apoptotic protein Bim and a decrease in the anti-apoptotic proteins Mcl-1, Bcl-2, Bcl-xl and survivin." (PMID 29262554, 2017). "However, the effect of miR-29 on Mcl-1 and gemcitabine-mediated cytotoxicity is not known in pancreatic cancer cells." (PMID 27626694, 2016). "Our results show Mcl-1 is up-regulated in pancreatic tumors but not in the adjacent normal tissue." (PMID 24025188, 2013). "We found that YM155 exerts an anti-proliferative effect in pancreatic cancer cells, inducing cell death through suppression of XIAP (X-linked inhibitor of apoptosis) as well as survivin without affecting the anti-apoptotic proteins Bcl-xL or Mcl-1." (PMID 22723871, 2012). "The lack of sensitization to gemcitabine by GSK-3 inhibition in pancreatic cancer might be due to number of reasons: 1) Some of the proteins targeted by GSK-3 for proteasomal degradation, including Mcl-1, β-catenin, and cdc25, have cancer-promoting effects." (PMID 19405981, 2009).
chronic lymphocytic leukemia (74 papers, 2010 to 2025). "CDK9 is also responsible for transcription of anti-apoptotic factors, that belong to Bcl-2 superfamily: Mcl-1 (Myeloid cell leukaemia-1), Bcl-2 (B-cell CLL/Lymphoma 2), and XIAP (X-linked inhibitor of apoptosis), making CDK9 potential source of inhibition for anti-tumor purposes." (PMID 33805800, 2021). "For example, in multiple studies, increased levels of Bcl-2, Bcl-xL, and Mcl-1 proteins were linked to survival of multiple myeloma cells and resistance to chemotherapy, while in most cases of chronic lymphocytic leukemia (CLL), elevated Bcl-2 mRNA and protein levels are noted." (PMID 23233904, 2012). "Cyclin-dependent kinase (CDK) inhibitors such as flavopiridol is one such class of compounds that has been shown to potently downregulate Mcl-1 expression in B-cell chronic lymphocytic leukemia (CLL) that resulted in patients with high risk and refractory CLL." (PMID 36045907, 2022). "In another study comparing ibrutinib and R406, it was demonstrated that R406 has a stronger pro-apoptotic effect through Mcl-1 downregulation than ibrutinib in chronic lymphocytic leukemia (CLL) samples." (PMID 41221328, 2025). "Specifically, SYK-mediated AKT activation inhibits GSK3 (glycogen synthase kinase 3), preventing the ubiquitination and proteasomal degradation of MCL-1, a key anti-apoptotic protein in chronic lymphocytic leukemia (CLL) and other malignancies." (PMID 40507977, 2025). "For instance, MI-2 significantly decreased anti-apoptotic proteins such as BCL2 and MCL-1 (myeloid leukemia 1) and activated the intrinsic apoptosis pathway in chronic lymphocytic leukemia." (PMID 38097554, 2023). "Several cellular regulatory processes, such as the modulation of lymphoid transcription and the AMPK/PKA axis, cellular energy metabolism, and overexpression of MCL1, contribute to venetoclax resistance in chronic lymphocytic leukemia." (PMID 37679323, 2023). "IFN-gamma has been reported to promote the survival of primary chronic lymphocytic leukemia (CLL) cells via JAK-Src/STAT3/Mcl-1 signaling pathway, with elevated IFN-gamma levels characteristic for advanced Rai stage disease." (PMID 35741122, 2022). "The AKT/ MCL-1 signaling pathway has been reported to play a prominent role in mediating antiapoptotic signals in chronic lymphocytic leukemia B cells or in resistance to BCL-2/PARP inhibitors, or BH3 mimetics." (PMID 35136016, 2022). "It has been reported that the transcript levels of STAT3-regulated anti-apoptotic genes Bcl-2 and MCL-1 or proapoptotic gene such as caspase-3 were both upregulated in Chronic lymphocytic leukemia (CLL) cells from patients and myeloid cells." (PMID 36615735, 2022). "Inhibition of antiapoptotic proteins as a monotherapy, (specifically Bcl-2, Bcl-xL, and Mcl-1) is a successful cancer treatment strategy for acute myeloid leukemia, chronic lymphocytic leukemia, and small lymphocytic lymphoma." (PMID 36381235, 2022). "High levels of Mcl-1 and Bcl-2 have been identified in B-cell chronic lymphocytic leukemia (CLL), a type of cancer that is extremely resistant to many types of treatment." (PMID 33805800, 2021). "The suppression of Axl in chronic lymphocytic leukaemia (CLL) reduced levels of the anti-apoptotic protein MCL-1 and stimulate apoptosis." (PMID 33806258, 2021). "In conclusion, the present study indicated that miRNA-15a acted in concert with fludarabine to exert synergistic anticancer efficacy against chronic lymphocytic leukemia, which attributed to the down-regulation of Mcl-1 and Bcl-2." (PMID 34319043, 2021). "In chronic lymphocytic leukemia (CLL) and multiple myeloma (MM), high levels of MCL1 are associated with the shortest progression free survival." (PMID 32645016, 2020). "The JAK2/STAT3 in particular has a key role in conveying signals that elicit the transcription of pro-survival and anti-apoptotic genes, such as Mcl-1 and Bcl-2, both known to be over-expressed in chronic lymphocytic leukemia (CLL)." (PMID 31817171, 2019).
chronic lymphocytic leukemia (continued). "In this regard, HHT has been shown to down-regulate MCL-1 in human acute and chronic myeloid leukemia cells, chronic lymphocytic leukemia cells, and MM cells." (PMID 30445933, 2018). "One study in chronic lymphocytic leukemia (CLL) also suggested that AXL inhibition mediates apoptosis by reducing the expression of the anti-apoptotic protein MCL1." (PMID 28251492, 2017). "In particular, a deregulated CDK9 pathway increases the expression of myeloid leukemia cell differentiation protein (Mcl-1), as shown by studies on biopsies obtained from patients with either advanced chronic lymphocytic leukemia or multiple myeloma." (PMID 23840966, 2013). "Besides its role in MLL, P-TEFb is also involved in the pathogenesis of AML and chronic lymphocytic leukemia (CLL) through its direct role in myeloid cell leukemia 1 (MCL-1) transcription." (PMID 34041038, 2021). "Hence, inhibitors specific for Bcl‐2 or Mcl‐1 have been developed as direct inducers for tumor cell apoptosis in chronic lymphocytic leukemia and small lymphocytic lymphoma, and hamper tumor progression both in patients and in tumor mouse models." (PMID 34766113, 2020). "Furthermore, silencing of the splicing factor SF3B1 or SRSF1 has been shown to induce splicing alteration of MCL1, which subsequently reduces Mcl-1L protein expression by chronic lymphocytic leukaemia cells." (PMID 33064779, 2020). "Several studies have demonstrated that HHT could induce apoptosis via inhibition of protein synthesis and down-regulation of Mcl-1 in chronic lymphocytic leukemia and myeloid leukemia cells." (PMID 29788973, 2018). "Low expression of Mcl-1 mRNA is correlated with prolonged survival in B-cell CLL." (PMID 21750559, 2011). "B-cell receptor (BCR) signaling pathway and Bcl-2 family prosurvival proteins, specifically Bcl-2 and Mcl-1, are functional in the pathobiology of chronic lymphocytic leukemia (CLL)." (PMID 35273915, 2022). "Previous studies have shown that Bisindolylmaleimide IX could induce apoptosis by cleaving anti-apoptotic protein Mcl-1 in chronic lymphocytic leukemia (CLL) cells, a disease not caused BCR-ABL, and induce apoptosis in HL-60." (PMID 27564101, 2016). "In vivo anti-tumor activity has been shown for silvestrol in hematological malignancies such as chronic lymphocytic leukemia, acute lymphocytic leukemia and mantle cell lymphoma, likely through the depletion of short half-life pro-growth or pro-survival proteins including cyclin D and Mcl-1." (PMID 24086701, 2013). "H3B-8800 modulates MCL1 alternative splicing and displays synergistic effects with the BCL2 inhibitor Venetoclax in chronic lymphocytic leukemia (CLL) cells." (PMID 39885614, 2025). "Myeloid cell leukemia-1 (MCL-1) is a potent anti-apoptotic protein and a crucial member of the BCL-2 (B-cell CLL/Lymphoma 2) protein family." (PMID 38027013, 2023). "Encouraged by the design of venetoclax and its efficacy in chronic lymphocytic leukemia, scientists have developed other BCL-2 homology (BH3) mimetics—particularly MCL-1 inhibitors (MCL-1i)—that are currently in clinical trials for various cancers." (PMID 37601693, 2023). "TP-0903 reduces anti-apoptotic proteins like BCL-2, MCL-1, and XIAP, and enhances dose-dependent chronic lymphocytic leukemia (CLL) cell death." (PMID 35311091, 2022). "For example, in patients with chronic lymphocytic leukemia (CLL), low MCL1 expression and high BIM:MCL-1 or BIM:BCL-2 ratios correlate with increased response to navitoclax (BCL-2/BCL-XL/BCL-W inhibitor)." (PMID 35008216, 2021).
chronic lymphocytic leukemia (continued). "For example, miR-15a as a tumor suppressor can target multiple oncogenes such as BCL2, MCL1, CCND1, and WNT3A, and plays a role in cancers such as Chronic Lymphocytic Leukemia (CLL), pituitary adenomas, and prostate carcinoma." (PMID 31434294, 2019). "miR-15a, along with miR-16, is commonly deleted in human chronic lymphocytic leukemia and known to target multiple oncogenes, including BCL2, MCL1, CCND1, and WNT3A." (PMID 23557329, 2013). "In fact, the use of kinase inhibitor in clinical trials for the treatment of patients with chronic lymphocytic leukemia showed that the inhibition of CDK9- and CDK7-related pathways was responsible for the decrease of the antiapoptotic factor Mcl-1." (PMID 23840966, 2013). "However, elevated levels of Mcl-1 have been reported for a number of solid tumors and B-cell chronic lymphocytic leukemia (B-CLL) as well as and AML and acute lymphoid leukemia (ALL) upon relapse." (PMID 21304176, 2010). "In chronic lymphocytic leukemia (CLL), the lymph node (LN) microenvironment delivers critical survival signals by inducing the expression of anti-apoptotic Bcl-2 members Bcl-XL, Bfl-1, and Mcl-1, resulting in apoptosis blockade." (PMID 33495554, 2021). "It has been shown that bcl2, bcl-XL and mcl-1 protein levels are high in chronic lymphocytic leukemia cells, and resultantly, apoptosis does not occur chronic lymphocytic leukemia cells." (PMID 31718601, 2019). "Thus it has been shown that both UCN-01 and flavopiridol decrease the expression of Mcl-1, XIAP, BAG-1, and Bcl-2 in B-cell chronic lymphocytic leukemia cells." (PMID 23527225, 2013). "Further, while being effective in cancers that depend on BCL2 for survival, such as chronic lymphocytic leukemia (CLL), resistance to ABT-199, as well as other inhibitors of BCL2, can occur through upregulation of other anti-apoptotic proteins such as BCL-XL, BFL1 (BCL2A1), or MCL1." (PMID 32824203, 2020). "Here we are the first to report that GPR65 is expressed in primary human Chronic Lymphocytic Leukemia (CLL) cells and that GPR65 expression levels in these cells correlate strongly with expression levels of the anti-apoptotic Bcl-2 family members Bcl-2, Mcl-1, and Bcl-xl." (PMID 25984552, 2014).